FRYL (FRY like transcription coactivator)
Description:
Plays a key role in maintaining the integrity of polarized cell extensions during morphogenesis, regulates the actin cytoskeleton and plays a key role in patterning sensory neuron dendritic fields by promoting avoidance between homologous dendrites as well as by limiting dendritic branching (By similarity). May function as a transcriptional activator.
Synonyms: AF4P12; KIAA0826; DKFZp686E205; MOR2; PCBS
Tractability: PROTAC: ubiquitination databases record sites on it; its protein half-life has been measured.
Gene: Protein-coding gene on chromosome 4 (48,497,357 to 48,780,322, reverse strand). Ensembl gene ENSG00000075539.
Subcellular location (Human Protein Atlas): Cytosol; Cytokinetic bridge; Microtubules
Gene Ontology:
Molecular function: protein binding
Biological process: cell morphogenesis; neuron projection development
Cellular component: cell cortex; site of polarized growth
Genetic constraint (gnomAD): Loss-of-function variants: 67 observed, 189.29 expected, observed/expected ratio (o/e) 0.35, 90% interval 0.29 to 0.43. The upper end of that interval is the gene's LOEUF score, 0.43, which puts it in group 1 of 6, group 1 being the genes least tolerant of losing a copy. Missense variants: 2,028 observed, 2,480.8 expected, observed/expected ratio (o/e) 0.82, 90% interval 0.79 to 0.85. Synonymous variants: 811 observed, 883.19 expected, observed/expected ratio (o/e) 0.92, 90% interval 0.87 to 0.97.
Homologues: Orthologues: chimpanzee FRYL (99% identical), macaque FRYL (99% identical), rabbit FRYL (97% identical), dog FRYL (97% identical), guinea pig FRYL (97% identical), pig FRYL (97% identical), mouse Fryl (94% identical), rat Fryl (94% identical), tropical clawed frog fryl (88% identical), zebrafish fryl (81% identical), Drosophila melanogaster fry (40% identical), Caenorhabditis elegans sax-2 (28% identical). Paralogues in human: FRY (61% identical).
Diseases named in the same sentence as FRYL in open-access papers:
FRYL is named in the same sentence as 18 diseases in open-access papers, as found by Europe PMC text mining. Sharing a sentence is not in itself a finding about the gene and the disease. The quoted sentences say what the papers report.
developmental delay (2 papers, 2024 to 2025). "De novo variants in FRYL are associated with developmental delay, intellectual disability, and dysmorphic features." (PMID 39590469, 2024).
acute leukemia (1 paper, 2019). A clonal (malignant) hematopoietic disorder with an acute onset, affecting the bone marrow and the peripheral blood. "However, FRYL is an important gene in therapy‐related acute leukemias, while KIAA1683 and SHC1 might be novel cancer genes." (PMID 30828525, 2019).
acute lymphoblastic leukemia (1 paper, 2021). Leukemia with an acute onset, characterized by the presence of lymphoblasts in the bone marrow and the peripheral blood. "Very little is known about FRYL, however, the c-terminus of FRYL is often observed to be fused to the mixed lineage leukemia (MLL) gene associated with treatment related acute lymphoblastic leukemia (ALL)." (PMID 34386489, 2021). "FRYL was first identified as a novel fusion partner of the mixed lineage leukemia (MLL) gene that was reported in patients who developed treatment-related acute lymphoblastic leukemia (ALL)." (PMID 34386489, 2021).
autism (1 paper, 2021). Persistent deficits in social interaction and communication and interaction as well as a markedly restricted repertoire of activity and interest as well as repetitive patterns of behavior. "Additionally, 4 novel genes, POGZ, KDM5B, NAA15, and FRYL, harbored at least two de novo mutations in both CHD and autism cohorts." (PMID 34735430, 2021). "From this table, we can see CDK13, FRYL, LZTR1, NAA15 and PTEN have 2 DNM counts for CHD and at least 1 shared DNM count with autism." (PMID 34735430, 2021).
Hypertension (1 paper, 2017). The presence of chronic increased pressure in the systemic arterial system. "Up to this point our findings supported the view that NOTCH signaling provides a constitutive drive for aortic sGC expression in the mouse aorta that is disturbed by hypertension via repression of the coactivators MAML2 and FRYL." (PMID 28465505, 2017). "In summary, our work argues that Notch signaling provides a constant drive on expression of sGC in arterial smooth muscle and that this is perturbed by hypertension via reduction of the transcriptional coactivators MAML2 and FRYL." (PMID 28465505, 2017).
Neurodevelopmental delay (1 paper, 2025). "FRYL has been associated with neurodevelopmental delay and dysmorphic features, but its role remains incompletely defined, and technical sequencing artifacts cannot be excluded." (PMID 41375745, 2025).
prostate benign tumors (1 paper, 2021). "Additionally, we observed that FRYL mRNA expression was significantly higher in CRPC and NEPC patient tumor samples, when compared to prostate benign tumors." (PMID 34386489, 2021).
prostate carcinoma (1 paper, 2021). A carcinoma that arises from epithelial cells of the prostate gland. "To examine the differential expression patterns of FRYL in PCa, we first evaluated the mRNA expression of FRYL by RNAseq in a subset of prostate cancers." (PMID 34386489, 2021).
Stroke (1 paper, 2017). Sudden impairment of blood flow to a part of the brain due to occlusion or rupture of an artery to the brain. "Reduced expression of sGC, correlating with differential expression of MAML2, in stroke prone and spontaneously hypertensive rats was also seen, and RNA-Seq data demonstrated correlations between JAG1, NOTCH3, MAML2 and FRYL and the sGC subunits GUCY1A3 and GUCY1B3 in human coronary artery." (PMID 28465505, 2017).
cancer (5 papers, 2017 to 2021). A tumor composed of atypical neoplastic, often pleomorphic cells that invade other tissues. "Therefore, it will be interesting to further investigate the role of FRYL as a transcription factor and its possibility to act as a fusion partner for genes involved in cancer progression." (PMID 34386489, 2021).
tumor (3 papers, 2021 to 2025). "We were interested in the mechanisms involved in the tumor suppressor role of miR-1205 and therefore we examined the putative targets of miR-1205 where FRYL was identified and validated as a target of miR-1205." (PMID 34386489, 2021). "Our data suggests that miR-1205 may have tumor suppressive functions through the regulation of FRYL in CRPC PCa." (PMID 34386489, 2021). "FRYL expression is significantly higher in CRPC and NEPC patient tumor samples when compared to prostate benign tumors (Wilcoxon test; benign vs. CRPC p = 6.6e-05, benign vs. NEPC p = 0.00025, PCa vs. CRPC p = 8.5e-07, and PCa vs. NEPC p = 4.5e-05)." (PMID 34386489, 2021).
cardiovascular disease (1 paper, 2017). "We find that both MAML2 and, albeit to a lesser extent, FRYL have the capacity to independently drive sGC expression, making them potential targets for prevention of cardiovascular disease caused by an elevated blood pressure." (PMID 28465505, 2017).
FRYL also shares sentences with these, for which no sentence is quoted: Intellectual disability (2 papers); benign tumors (1); lymphoid leukemia (1); lymphoma (1); prostate (1); small cell prostatic carcinoma (1).